PI4KAP2 (phosphatidylinositol 4-kinase alpha pseudogene 2)
Gene: Transcribed unitary pseudogene on chromosome 22 (21,473,059 to 21,488,358, reverse strand). Ensembl gene ENSG00000183506.
Diseases named in the same sentence as PI4KAP2 in open-access papers:
PI4KAP2 is named in the same sentence as 1 disease in open-access papers, as found by Europe PMC text mining. Sharing a sentence is not in itself a finding about the gene and the disease.
PI4KAP2 shares sentences with these, for which no sentence is quoted: Alzheimer disease (1 paper).